TNF (tumor necrosis factor)
Diseases named in the same sentence as TNF in open-access papers (continued):
Sharing a sentence is not in itself a finding about the gene and the disease.
infection (continued). "The pro-inflammatory cytokines upregulated during infection include IL-6 and TNF-α, and highly upregulated chemokines MIP-1α, MCP-1, and RANTES." (PMID 36071442, 2022). "Decreased levels of cytokine molecules (TNF-α, IL-1β) represent a reduction of cellular immunological function, which ultimately results in a high infection rate under external stressors." (PMID 35328551, 2022). "The protein levels of IL-1β, IL-6, and IFN-β were highest after infection of 12 h, but TNF-α was maintained in the higher levels after 24 h." (PMID 35458442, 2022). "IL-6 and TNF-α are inflammatory cytokines synthesized by many cell types such as monocytes, macrophages, and fibroblasts in response to infections, and play pivotal roles as signal molecules involved in various immune responses." (PMID 35167625, 2022). "The TNFα and IL-6 levels in CXCR4high MKs were comparable to macrophages from mice 3 days after L. monocytogenes infection, which are known as the primary cellular source of TNFα and IL-6 upon infection." (PMID 35904250, 2022). "TLR4 constitutes one of the key players of the innate immune system, and is activated in response to an infection, resulting in NF-kB mediated production of pro-inflammatory cytokines, such as TNFα and IL-6." (PMID 36613673, 2022). "This infection induces the recruitment of M1 macrophages as detected by a high level of TNFα expression." (PMID 35200139, 2022). "In the early stage of infection, classically activated macrophages can produce a group of proinflammatory cytokines such as interleukin 6 (IL-6), IL-12, and tumor necrosis factor alpha (TNF-α)." (PMID 35328497, 2022). "MΦs increase Mincle expression via feed-forward mechanisms, TNFα-mediated mechanisms, or stimulation with DAMPs as the infection progresses." (PMID 36678402, 2022). "T lymphocytes produce IL-1, IL-6, IL-12, interferon (IFN)-γ, and TNF-α, which function as chemo-attractants to recruit leukocytes at the site of infection." (PMID 35203344, 2022). "The results showed that the levels of IL-4, IFN-γ and TNF-α increased, and the levels of IL-10 decreased after infection with T. gondii." (PMID 36245502, 2022). "More detailed time-course of infection studies will be needed to relate IL-10 activation/expression with changes in other cytokine levels (e.g., IL-1β and TNFα)." (PMID 35911725, 2022). "In cats experimentally infected with B. henselae, the number of CD4+ T-lymphocytes decreased after infection, and interferon-γ and tumor necrosis factor-α were identified as important keys in eliminating B. henselae infection." (PMID 36425135, 2022). "We found that infection with S. pneumoniae expressing Ply suppressed tumour necrosis factor (TNF) and interleukin‐6 production by MDMs compared to cells infected with ply‐deficient S. pneumoniae." (PMID 35835695, 2022). "The increase in IL-10 can promote a more balanced immune response in these animals, keeping the levels of pro-inflammatory cytokines within ranges compatible with infection control and regulating the inflammation caused by IL-12, IFN-γ, and TNF." (PMID 35154155, 2022). "Instead, in these animal models T-cells and in particular IFNγ and TNFα responses are critical for controlling early infection and mediating bacterial clearance." (PMID 35812430, 2022). "Infection of F. nucleatum led to generation of IL-6 and TNF-α and they were inhibited by pretreatment with MAE significantly." (PMID 35564380, 2022). "cadC also participates in the regulation of virulence in L. monocytogenes which, in turn, alters the repertoire of proinflammatory cytokines (such as TNF-α and IL-6) produced by the host in response to infection." (PMID 36104331, 2022). "Next, cytokines were quantified at 24 and 72 h after the infection, and the results showed that the Mexico strain induced an increase in the secretion of the inflammatory cytokines TNF-α and IL-12." (PMID 35562916, 2022).
infection (continued). "We found, by TNF-α−/− mouse infection assay, that TNF-α plays an important role in the depletion of splenocytes." (PMID 36287014, 2022). "This study found that following TTPB, there are significant changes in some inflammatory and infection biomarkers, namely uB2MG, IL-6, IL-8, IL-10 and TNF-α." (PMID 36154663, 2022). "The evaluations of cytokine mRNA expression indicated that, both the Th1 (IFN-γ, TNF-α, IL-12) and the Th2 (IL-4 and IL-10) types of cytokines were differentially upregulated during the early stage of infection." (PMID 35215986, 2022). "The blood of mice was collected 12 h after infection and the inflammatory factors (including IL-1β, IL-6, and TNF-α) in serum were measured." (PMID 35493470, 2022). "For example, using TSA to induce chromatin remodeling at the LTR promoter is a clinical strategy to reactivate latent HIV reservoirs to clear the infection, and this has been found to synergize with TNF and other NF-κB activators." (PMID 36084132, 2022). "By contrast, the TNF-α and IL-6 levels in hcp1MVs- and hcp1MVs/adjuvant-immunized mice five days postchallenge decreased continuously after day 0.5 of infection (except TNF-α)." (PMID 36618368, 2022). "During infection, Brucella outer membrane protein 25 interferes with the production of TNF-α and other pro-inflammatory cytokines to promote its survival and immune evasion." (PMID 35955474, 2022). "Pathways related to genes modulated by TNFα/IFNγ involved pro-inflammatory signaling, infection, MAPK, and Ca2+ signaling." (PMID 35578269, 2022). "It is worth mentioning that when Css54 and MCP-1 were applied in combination, there was a clear increase in the expression of IL-10 and TNF-α while other cytokines remained at the same level that those presented in the infection group." (PMID 35625251, 2022). "TNF-α, a pro-inflammatory cytokine, is one of the early immune genes expressed at the beginning of infection and has a key part in controlling inflammation." (PMID 35859110, 2022). "Deficiency of TNFR1/2 resulted in greatly decreased numbers of CD69+ activated NK cells as early as D3, suggesting a key role of TNF signaling in regulating NK cell activation early during infection." (PMID 35479068, 2022). "IL-6 and TNF-α were significantly elevated on day one after infection, and the expression trends of plasma cytokines in mice on days 1, 3, and 5 of the experiment were inconsistent and did not correspond completely to the elevated plasma levels of CyPA." (PMID 36569095, 2022). "Some cytokines such as IL-6 and IL-10 have also been shown to reduce systemic IFN-γ and TNF-α, reduce number of trypanosomes in the CNS and to protect against the neuroinflammatory pathology that occur during infection." (PMID 35222377, 2022). "We observed that after sixteen hours of infection monocytes produced a significant amount of IL-1β, TNF-α, IL-6 and IL-10 in response to viable fungal spores." (PMID 36311802, 2022). "The primary role of TNF-α, IL-1β, and IL-6 is the regulation of inflammatory response when wounded, and during infection or immune stimulation." (PMID 35161266, 2022). "Evidently, TNF-α can trigger robust cell death by activating apoptotic signaling pathway, and blocking TNF-α with neutralizing antibodies in a murine infection model can significantly reduce SARS-CoV-2 induced mortality." (PMID 36182930, 2022). "Numerous inflammatory cells, mainly macrophages, dendritic cells, polymorphonuclear neutrophils, and inflammatory cytokines (TGF-β, TNF-α, IL-1β, IL-6, IL-10, IL-12, and IL-23), were activated in the early stages of infection." (PMID 36233337, 2022). "In order to investigate role of this receptor in the HAdV26-induced expression of IL-6 and TNF-α, we downregulated the amount of αvβ3 integrin by using specific siRNA in SK-OV-3 cells prior to HAdV26 infection." (PMID 35458402, 2022).
infection (continued). "CXCL-8 and TNF-α are directly involved in the recruitment of additional macrophages to the infection site, which results in the breaking of the endothelial barrier." (PMID 35446128, 2022). "The optimized approach was associated with more robust Th1 (IFN-γ, TNF-α, IL-2) and Th17 responses (IL-17A) systemically (spleens and PBMCs), but also in the lungs and draining LNs (IFN-γ and IL-17A), the primary site of infection." (PMID 36189260, 2022). "Adverse events attributed to anti-TNF therapy occurred in 23 participants and included the following: infection (n = 19), psoriaform rash (n = 2), headache (n = 2)." (PMID 35075155, 2022). "When we assessed T-helper (Th) cell immunity, SARS-CoV-2-specific Th cells produced detectable amounts of IFNγ and TNF six weeks after the infection." (PMID 35062775, 2022). "The mRNA expression level of IL-1β and TNFα has shown an increasing trend in Rag2−/− mice following SARS-CoV-2 MA10 infection." (PMID 36680154, 2022). "After infection, production of IL-12p40, IL-6 and IL-10 was significantly reduced in AM compared to M1 and M2 macrophages while the production of TNFα was intact." (PMID 36776396, 2022). "According to real-time PCR, the mRNA level of IL-1, IL-6, and TNF-α decreased significantly in KO mice compared with WT mice on Days 5 after infection." (PMID 35163412, 2022). "Elevated pro-inflammatory cytokine levels were detected for WNV infection at 48- and 72-h post-infection, with key inflammatory cytokines IL-1β, TNF-α, IL-6 and IL-8 showing a statistically significant increase." (PMID 36297275, 2022). "Tissue damage and infection induce the activation and release of proinflammatory cytokines, such as IL-1β, IL-2, IL-8, and TNF-α, which mediate the onset of innate immune response." (PMID 36860473, 2022). "Proinflammatory cytokines associated with Th17/Th1 response such as IL-6, TNF-α, and IL-1β, and neutrophil-recruiting chemokines including CCL2, CCL3, CXCL1, and CXCL2 were highly produced from day 3 to day 14 after WT infection." (PMID 35696422, 2022). "Consistent with this, after AH1 infection, the levels of interleukin-6 (IL-6), tumor necrosis factor-alpha (TNF-α) and interleukin-1β (IL-1β) significantly increased in the lung tissues of p21˗/˗ mice compared with WT mice." (PMID 35180274, 2022). "Mean concentrations of IL-6, IL-1β, and TNF-α pre infection were 0.69 ± 0.27 pg/mL, 0.07 ± 0.03 pg/mL, and 0.32 ± 0.06 pg/mL (mean ± SE), respectively." (PMID 35281029, 2022). "In this study, MAC-T cells were treated with MRSA and MSSA at different time points: The expression of TNF-α, IL-6, phosphorylated p65, and cleaved-Caspase3 expression varies with the time of infection." (PMID 35812882, 2022). "Respective analysis of the downregulated DEGs demonstrated modulation of several pathways, some of which were also downregulated in Brucella-infected Mφ at 2h post-infection, such as TNF signaling and herpes simplex virus 1 infection." (PMID 35979363, 2022). "Beyond that, the changes of inflammatory factors at different time points also found that the expression of IL-6, TNF-α, and IL-8 was increased in BMECs after M. bovis infection and showed a change dependent on infection time and MOIs." (PMID 35464378, 2022). "This was linked to reduced serum concentrations of the pro-inflammatory cytokines (IFNɣ, TNF, and IL-6) and an increase in the IL-10 serum concentration, especially during the chronic stage of infection." (PMID 35464430, 2022). "In the case of A549 cells infected with H3N2 in the presence of ghA, ghB or ghC modules, TNF-α was downregulated 2 h post-infection by ghA (~−0.29 log10) and ghC (~−0.11 log10)." (PMID 35328462, 2022). "After 48 h of infection, the levels of TNF, CXCL8, IL6, CSF2, CD180, CD14, and CCL2 levels increased and those of IL-10, INFB1, and CXCL10 decreased." (PMID 36296238, 2022).
infection (continued). "As for the protein levels of cytokine profiles in the ileum, DON infection induced dramatic increases in the expression of ileal IL-1β, TNF-α and IL-6 proteins (p < 0.01)." (PMID 36139849, 2022). "During the inflammatory period, macrophages secrete pro-inflammatory factors (IL-1β, TNF-α, IL-6, etc.)and anti-inflammatory factors (IL-10) to clear the necrotic tissue and prevent infection at the wound site." (PMID 35877710, 2022). "Our results indicate that there must be an effective anti-inflammatory response in the CNS to avoid tissue damage induced by pro-inflammatory cytokines or neutrophils, since both the production of TNF-α and neutrophil recruitment decreased 24 h post-infection." (PMID 35742984, 2022). "By regulating crucial immunological processes, such as dampening the impact of TNF-α, and boosting the Treg responses, they augment the defence against infection." (PMID 36532032, 2022). "Infection with either virus also resulted in an induction of the pro-inflammatory genes CXCL8 (encoding IL-8), IL6 and TNF, albeit to a lesser extent in SARS-CoV-2-infected cells." (PMID 35840680, 2022). "We had previously shown that anti-N CD8+TNF-α+ T cells were generated upon acute infection in children, while adults focused that response on S peptides." (PMID 36405692, 2022). "We found that the mRNA expression levels of TNF-α, IL-1β and IL-6 were significantly increased after 7 days of infection, while the expression of the three inflammatory factors was decreased upon intraocular injection of LBH589." (PMID 36171756, 2022). "Upon infection with the HX strain, the KEGG pathways were observed to be enriched in the immune-associated pathways such as TNF and IL-17 signaling." (PMID 35234615, 2022). "Once neutrophils are recruited to the site of infection, inflammatory mediators in the local environment, such as TNF-α, G-CSF, and GM-CSF, are necessary to promote the activation of neutrophils in inflamed tissues." (PMID 34990413, 2022). "Surprisingly, the TNF-α levels of cells infected with ΔbepD and ΔbepA-I strains were lowered to similar extent as in wild-type infections." (PMID 35910598, 2022). "It is well-established that following the acute phase of infection or during the first six weeks of infection, the immune response to S. mansoni is predominantly Th1, characterised by the abundant production of TNF-α, and IFN-γ." (PMID 35163381, 2022). "Infection of MDM with the γ-P.1 (Brazil) and β-B.1.351 (South Africa) variants resulted in highest TNF-α secretion by γδ2 T cells (p=0.0324 and p=0.0101, respectively)." (PMID 36601113, 2022). "CRP gene transcription is initiated in response to tissue damage, infection, or proinflammatory cytokines such as interleukin-6 (IL-6) and tumor necrosis factor (TNF)." (PMID 35821205, 2022). "Several studies revealed that CD8+ T-cell-derived granzyme B and TNF-α were implicated in IV-mediated lung injury, and inhibition of TNF-α signaling in CD8+ T cells markedly relieved lung injury after IV infection." (PMID 36180831, 2022). "Serum TNF-α levels remained similar for sterile implants or after infections with implants or for infected tissues." (PMID 35203495, 2022). "Six hours post-infection, TNF-α mRNA levels were upregulated in A549 cells challenged with C1q-treated H1N1 (~0.15 log10) or H3N2 (~0.4 log10)." (PMID 35328462, 2022). "The acutely infected group had a significant decrease in TNFα expression following infection, but by Visit 3 TNFα expression had returned to levels observed at enrollment." (PMID 35422803, 2022). "It was found that infection of NPCs isolated from developing mouse brains with ZIKV (MEX1-44) resulted in a sharp increase of tumor necrosis factor (TNF-α)." (PMID 35371036, 2022). "When infection or inflammation is severe enough to affect organs, macrophages first show M1 phenotype and release TNF-α, IL-12, and IL-23 antagonized stimulation." (PMID 35653001, 2022).
infection (continued). "Our results showed that the lower the level of Sirt3, the worse the indicators of inflammation (TNF-α, IL-6) and infection (PCT), a result that was expected." (PMID 35729330, 2022). "BCGΔBCG1419c-elicited protection also associated with lower levels of proinflammatory cytokines (i.e. IL6, TNFα) at the site of infection in C57BL/6 mice." (PMID 35858977, 2022). "After 2 h of infection, the levels of IL-6 and TNF-α increased in the E. coli E44 group, when compared to the control group." (PMID 36289622, 2022). "Th1 cytokines (IL-1β, IL-2, IL-12p70, IFN-γ and TNF-α), Th2 cytokine (IL-4), as well as Th17 cytokine (IL-17A) showed decreasing trend by infection intensity." (PMID 36083861, 2022). "Proinflammatory cytokines such as TNF alpha, that promotes bone resorption and mediates the inflammatory response to infection, can be used to evaluate the level of inflammation." (PMID 35292688, 2022). "In comparison, an S variant proliferates to high burdens but appears to be controlled by TNF-dependent innate immunity early during infection, resulting in delayed granuloma formation." (PMID 35177649, 2022). "Improper secretion of TNF is involved in the pathogenesis of various human diseases, including infection, transplant rejection, cancer, inflammatory diseases, and pulmonary fibrosis." (PMID 35168663, 2022). "The lowest TNF-α values were detected in infections by isolate 6 varying from 2.651 ± 0.12 pg/mL (24h), 5.61 ± 0.75 pg/mL (48h) and 1.21 ± 0.56 pg/mL (72h)." (PMID 35531337, 2022). "Tc1 cells are capable of producing IL-2, IFN-γ, and TNF-α, cytokines recognized for playing critical roles during infection." (PMID 35214766, 2022). "In one investigation, patients having severe disease showed augmented plasma levels of CXCL10, IFN-α, IFN-γ, and reduced levels of tumor necrosis factor alpha (TNF-α), IL-12p70 and IL-2 during the acute phase of infection." (PMID 36366313, 2022). "The inflammatory response of the body after infection initiates the NF-Kappa B signaling pathway, which induces the expression of cytokines such as IL-6, IL1β and TNF-a to eliminate pathogen invasion." (PMID 36091044, 2022). "Ex vivo studies show that pre-treatment of human neutrophils with TNF-α prior to infection enhances the killing of S. aureus." (PMID 36203565, 2022). "Lenti-Spike infection significantly increased the expression of inflammatory cytokines, including IL-1β, IL-6, and TNF-α, and chemokines, including CCL-2, CCL-3, CCL-4, and CXCL-10, whereas Lipo-hACE2 decoy significantly inhibited all these effects." (PMID 35401811, 2022). "To further investigate this assumption, we downregulated αvβ3 integrin in SK-OV-3 cells using specific siRNA for the β3 integrin subunit, and subsequently determined the gene expression of IL-6, IL-8 and TNF-α following HAdV26 infection." (PMID 35458402, 2022). "This complex case of infection, which was resolved by the removal of the dental implants and necrotic debris, was attributed to the TNF-a inhibitor treatment." (PMID 35334519, 2022). "The infection of A549 and SK-OV-3 with HAdV26 induced changes in the expression of the IL-6, IL-8, IL-1β, and TNF-α genes." (PMID 35458402, 2022). "This low production of TNF-α induced by lipid-cultured strains was increased at 24 hpi, particularly during infection with the mutant strain in the stationary phase." (PMID 35873160, 2022). "According to previous studies, infection in the human body generates circulating inflammatory cytokines, such as IL-1, -6, and -8 and TNF-α, which can activate inflammatory cells in atherosclerotic plaques to destabilize them." (PMID 35207717, 2022). "SphK2−/− mice had overall diminished levels of all investigated pro-inflammatory cytokines that did not significantly alter compared to naïve control levels except for TNF-α at 6 h post infection." (PMID 36361636, 2022).